TTLL8 (tubulin tyrosine ligase like 8)
Description:
Monoglycylase which modifies both tubulin and non-tubulin proteins, adding a single glycine to the gamma-carboxyl groups of specific glutamate residues to generate monoglycine side chains within the C-terminal tail of target proteins. Not involved in elongation step of the polyglycylation reaction. Preferentially monoglycylates alpha-tubulin over beta-tubulin. Together with TTLL3, mediates microtubule glycylation of primary and motile cilia, which is essential for their stability and maintenance. Together with TTLL3, glycylates sperm flagella which regulates axonemal dynein motor activity, thereby controlling flagellar beat, directional sperm swimming and male fertility. Monoglycylates non-tubulin proteins such as ANP32A, ANP32B, SET, NCL and NAP1.
Gene: Protein-coding gene on chromosome 22 (50,018,575 to 50,058,298, reverse strand). Ensembl gene ENSG00000138892.
Subcellular location: Cytoplasm, cytoskeleton; Cell projection, cilium; Cytoplasm, cytoskeleton, cilium axoneme; Cytoplasm, cytoskeleton, flagellum axoneme
Pathways (Reactome):
Metabolism of proteins: Carboxyterminal post-translational modifications of tubulin
Genetic constraint (gnomAD): Loss-of-function variants: 56 observed, 58.71 expected, observed/expected ratio (o/e) 0.95, 90% interval 0.77 to 1.19. The upper end of that interval is the gene's LOEUF score, 1.19, which puts it in group 5 of 6, group 1 being the genes least tolerant of losing a copy. Missense variants: 786 observed, 825.75 expected, observed/expected ratio (o/e) 0.95, 90% interval 0.9 to 1.01. Synonymous variants: 351 observed, 344.87 expected, observed/expected ratio (o/e) 1.02, 90% interval 0.93 to 1.11.
Homologues: Orthologues: chimpanzee TTLL8 (97% identical), macaque TTLL8 (90% identical), dog TTLL8 (69% identical), pig TTLL8 (69% identical), rabbit TTLL8 (68% identical), rat Ttll8 (67% identical), mouse Ttll8 (66% identical), Drosophila melanogaster TTLL3A (29% identical), Drosophila melanogaster TTLL3B (26% identical), zebrafish ttll6 (12% identical), Drosophila melanogaster TTLL6B (11% identical), Drosophila melanogaster TTLL15 (10% identical), and 1 more. Paralogues in human: TTLL3 (38% identical), TTLL6 (14% identical), TTLL10 (13% identical), TTLL2 (13% identical), TTLL7 (13% identical), TTLL12 (12% identical), TTLL9 (12% identical), TTLL13 (12% identical), TTLL4 (12% identical), TTLL1 (12% identical), TTLL11 (11% identical), KPRP (8% identical).